CERS5 (ceramide synthase 5)
Diseases named in the same sentence as CERS5 in open-access papers (continued):
Sharing a sentence is not in itself a finding about the gene and the disease.
tumor (12 papers, 2009 to 2024). "For instance, CerS1 produces ceramides(18:0), which inhibit tumor growth, while CerS5 and CerS6 generate ceramides (16:0),which are associated with anti-apoptotic effects in headand neck squamous cell carcinoma.The CerS1-specific inhibitor P053 reduces ceramide (18:0)levels in HEK 293 cells." (PMID 39944803, 2024). "CERS5 is known to be responsible for C16-ceramide synthesis that is critical for sphingolipid signaling, tumor growth, and cell apoptosis." (PMID 38662454, 2024). "Given that LCA, an established tumour promoter, has been implicated in CRC metastasis and is primarily presented within the colon, we examined the expression of Cers1, Cers2, Cers5, and CERK in LCA-stimulated human intestinal epithelial cells." (PMID 37298127, 2023). "To further study the role of CERS5 in CRC in miR-148a–deficient mice, we investigated whether depletion of its expression would inhibit tumor growth in CRC mouse models." (PMID 34914638, 2022). "Concentrated adenovirus carrying a Cers5 shRNA vector was administrated to AOM/DSS-treated miR-148a–/– mice, and tumor burden was assessed after mice were sacrificed on day 120 of administration." (PMID 34914638, 2022). "Results of detection of CERS5 protein levels also revealed that CERS5 level was significantly higher in tumor than nontumor after AOM/DSS induction." (PMID 34914638, 2022). "CerS5-ko mice showed a significantly reduced colon length and larger colon tumors than CerS5-wt mice, whereas neither colon length nor tumor volume significantly differed between AOM/DSS-treated CerS5wt/VilCre or CerS5fl/fl/VilCre mice." (PMID 32630271, 2020). "In contrast, the gene expression of CERS4 and CERS5, but not ASAH1, was significantly increased in HCC tumors than that in non-tumor adjacent tissues." (PMID 33803928, 2021). "Data mining of our previous human HCC transcriptome dataset showed that the gene expression of CERS2, CERS4, CERS5, and CERS6 was significantly increased in HCC tumors compared with that in non-tumor adjacent tissues, while no obvious difference was observed in ASAH1 gene expression." (PMID 33803928, 2021).
cancer (4 papers, 2017 to 2024). A tumor composed of atypical neoplastic, often pleomorphic cells that invade other tissues. "Bile acid, namely LCA, activated cancer-promoting genes including Cers1, Cers2, Cers5, and CERK in the cancerous HT-29 cell line in a miR125b-dependent way." (PMID 37298127, 2023). "However, there has been no investigation into the differential AS of CERS5 in cancers and its functional implications for tumorigenesis." (PMID 38662454, 2024).
infection (1 paper, 2025). The state of being infected such as from the introduction of a foreign agent such as serum, vaccine, antigenic substance or organism. "Analysis of the expression levels of genes involved in the de novo synthesis pathway of Cer in M2Φ did not reveal notable alterations upon Ctr infection, although Cer synthase 5 (CERS5) was upregulated." (PMID 40249190, 2025).
muscular disorders (1 paper, 2020). "These few cases are consistent with the notion that CerS1 and CerS5 may also be linked to muscular disorders in chronic diseases." (PMID 31692231, 2020).
myopathy (1 paper, 2020). A disease of the muscle in which the muscle fibers do not function properly. "Genetic deficiencies of CerS1 and CerS5 showed reduced caliber sizes of type 1 and type 2 muscle fibers, ragged red fibers as histological signs of myopathy, and reduced strength." (PMID 31692231, 2020).
CERS5 also shares sentences with these, for which no sentence is quoted: fatty liver (2 papers); adenocarcinoma (1); cardiovascular disease (1); cervical cancer (1); chronic kidney disease (1); colon (1); Glucose intolerance (1); head and neck squamous cell carcinoma (1); hypertrophy (1); melanoma (1); neural tube defect (1); neurodegenerative disease (1); ovarian carcinoma (1); retinal degeneration (1); sarcopenia (1); steatosis (1).